PDGFRA (platelet derived growth factor receptor alpha)
Diseases named in the same sentence as PDGFRA in open-access papers (continued):
Sharing a sentence is not in itself a finding about the gene and the disease.
tumor (continued). "Second, we combined Ppm1d with the relatively strong oncogene platelet-derived growth factor B (PDGFB) to increase tumor penetrance, but PDGF receptor alpha (PDGFRA) may be a more faithful alteration found in human DMG10." (PMID 41394550, 2025). "Identifying PDGFRA or PDGFRB rearrangements is critical, as imatinib effectively treats these conditions, whereas pemigatinib is approved for refractory FGFR1-rearranged neoplasms." (PMID 40508151, 2025). "PDGFC may directly trigger PDGFRA signaling in CAF-C7, in keeping with our data showing increased deposition of ECM and activation of PI3K signaling at tumor margin." (PMID 39870619, 2025). "High expression of PDGFRα/β has been observed in CAFs, vascular cells, and malignant cells, where these receptors play crucial roles in shaping an immunosuppressive TME, promoting angiogenesis, facilitating tumour growth, and fostering metastasis." (PMID 39780187, 2025). "PDGFRA was highly expressed in fibroblasts in both tumor and normal tissues without significant differences, suggesting patient-specific variability." (PMID 41184502, 2025). "The cells cultured in MSC medium expressed high levels of COL6A3+ TAF signature genes (COL6A3 and PDGFRA), whereas the tumor cells cultured in DMEM did not express these genes, confirming the accuracy of our isolation method." (PMID 41174767, 2025). "Previous work has shown that in limb muscles of cachectic mice‐bearing C26 tumours, PDGFRα is also expressed by Pax7+ cells of nonsatellite cell origin that accumulate in cachectic muscle, yet fail to differentiate." (PMID 39810606, 2025). "The results demonstrated that in PDX models with high PDGFRA expression, avapritinib treatment significantly inhibited tumor growth, whereas lenvatinib alone did not exhibit significant suppressive effects on tumor growth." (PMID 40336047, 2025). "Indeed, lenvatinib acts by inhibiting multiple receptor tyrosine kinases, including VEGFR1–3, FGFR1–4, PDGFRα, RET and KIT, thereby impairing angiogenesis and tumor proliferation." (PMID 40507289, 2025). "In the pediatric GBM, among the three tumor subtypes classified by DNA methylation landscape (MYCN, RTK1, and RTK2), it was found that MYCN was enriched for MYCN amplification, RTK1 enriched for PDGFRA amplification, and RTK 2 enriched for EGFR amplification." (PMID 38474286, 2024). "Moreover, 94% (15/16), showed high expression of PDGFRβ, 88% (14/16) exhibited the presence of PDGFRa, and 81% (13/16) showed similar expression in the tumor stroma, while high CD24 expression in the tumor was observed in 63% of cases (10/16)." (PMID 38791897, 2024). "In contrast, our findings show nearly universal staining of pan-oligodendrocyte lineage markers OLIG2 and SOX10, OPC makers PDGFRA and NG2 and developing oligodendrocyte marker Nogo-A in the tumour cells of DNET, MGNT and RGNT samples and an enrichment of OPC signature in DNET transcriptomes." (PMID 38764775, 2024). "Moreover, in these reports, PDGFRA and EGFR amplifications usually occurred in distinct tumor cell populations and rarely simultaneously in the same tumor cells, although a common parental origin was postulated based on mutation analysis." (PMID 38254850, 2024). "The collaborative signaling among EGFR, PDGFRα, PDGFRβ, and FGFR2 proteins could result in a synergistic effect on promoting tumor progression making them valuable targets for cancer therapy." (PMID 38338684, 2024). "Lenvatinib prevents tumor angiogenesis through inhibition of VEGFR-1, -2, and -3, and also blocks the proliferation of tumor cells through inhibition of FGFR-1, FGFR-2, FGFR-3, & FGFR-4, PDGFRα, RET, and c-KIT." (PMID 38622735, 2024). "In contrast, some miRNAs, such as miR-146a, stimulate the growth of new blood vessels in the tumour microenvironment (TME) by regulating the expression of breast cancer 1 (BRCA1) and platelet-derived growth factor receptor alpha (PDGFRA) to enhance angiogenesis in HCC endothelial cells." (PMID 38915826, 2024).
tumor (continued). "The diminished progenitor states and potential differentiation of tumor cells were corroborated by the induction of GALC protein expression, another oligodendrocyte maturation marker, in parallel with the reduced level of PDGFRA protein." (PMID 37760589, 2023). "C-myc showed intense expression in all our cases, while PDGFRA, HTERT, and pan-TRK gained expression in the local recurrence and the xenografted tumor and so may be indicative of disease progression." (PMID 37108696, 2023). "Thus, SH3BP2 silencing decreased oncogenic KIT/PDGFRA levels, reduced MITF levels, led to apoptosis in vitro, and decreased tumor growth in vivo." (PMID 36834926, 2023). "Uniquely, these new models do not require constitutively active PDGF/PDGFRA signaling to drive tumor development, allowing investigation of subtype-specific oncogenic mechanisms." (PMID 37011011, 2023). "Consistent with tumor suppression, pharmacological inhibition of TGF‐βR1 abrogated Bmal1‐deletion–triggered tumor fibrosis that showed reduced positive structures of FAP, α‐SMA, DESMIN, PDGFRα, and PDGFRβ." (PMID 37330661, 2023). "To determine whether the two CAF populations affect CD8+ T-cell activation within the pancreas of 4KC mice, we isolated PDGFRα+ CAFs and siCAFs from 4KC mice by FACS and cocultured them with a primary tumor cell line to generate CAF-conditioned medium." (PMID 38111825, 2023). "Firstly, the main limitation is that SEER database has shortcomings in information depth, lacking several important factors such as intraabdominal tumor rupture, margin status, and genetic mutation of KIT or PDGFRA." (PMID 37855869, 2023). "Given the role of tumor-derived Pdgfc in ER+ DTC survival and outgrowth, we assessed whether pharmacological inhibition of PDGFRα using imatinib limits metastatic outgrowth." (PMID 36914817, 2023). "The authors demonstrated that PDGFRα+, but not normal pancreatic fibroblasts, promoted tumor growth in vitro and in vivo." (PMID 37174079, 2023). "Comparing the TME and tumour cell samples, there were 5050 differentially expressed genes (DEGs) and 12,704 ribonucleic acid (RNA) DEGs, including known TME markers such as platelet-derived growth factor receptor alpha (PDGFRA)." (PMID 37627163, 2023). "Similarly, in the ER+ tumor cells used here, Pdgfra and PDGFRA mRNA and PDGFRα protein levels are negligible compared to those in mouse (CAF, 10T1/2) or human (MRC5) fibroblasts." (PMID 36914817, 2023). "Notably, amplifications of CDK4 and MDM2 and gain of PDGFRA, together with chromosome 4p gain were identified as newly acquired CNAs in YMG25R, as compared to the initial tumor YMG25P." (PMID 38012788, 2023). "The models described here allow evaluation of the unique tumor biology produced by specific partner alterations and investigation of their selective therapeutic targeting without the confounding presence of PDGF overexpression or mutant PDGFRA." (PMID 37011011, 2023). "In addition, similar to YMG25R parent tumor, YMG25R xenograft cells highly expressed phospho-PDGFRA, -AKT, and -ERK as well as CDK4 and MDM2, and phospho-Rb, as compared to sham control." (PMID 38012788, 2023). "Under expression of PTGS2 (READ) and PDGFRA (COAD and READ), over expression of MET & MMP9 (COAD and READ) were observed in the expression analysis using boxplots of genes between normal and tumor samples." (PMID 36110531, 2022). "Among the five critical genes previously obtained from survival and molecular docking analysis, MMP9 & MET were the upregulated in tumor samples (COAD and READ), while PDGFRA (COAD and READ) & PTGS2/COX-2 (READ) were downregulated according to the expression analysis by box plots." (PMID 36110531, 2022).
tumor (continued). "Surprisingly, PDGFRA-mutant GISTs showed an increased number of immune cells, compared with c-KIT-mutant GIST, and an overexpression of stimulatory cytokines (e.g., CXCL14) which additionally activate NK+, CD4+, and CD8+ cells, leading to tumor regression." (PMID 36612211, 2022). "Clusters 0, 1, 3, and 5 overexpressing PDGFRA and EGFR were annotated as tumor cells." (PMID 36138856, 2022). "Moreover, the PDGFRα and p-MLC staining largely overlapped, demonstrating that the contractile activity in the RT2 tumor microenvironment is mainly exerted by CAFs." (PMID 35454853, 2022). "The PD/SQ-derived and FR/SQ tumor-derived CAFs expressed high levels of fibroblast mRNA markers (via QPCR analyses) αSMA, PDGFRα and FAP, but very little or no epithelial cell marker EPCAM." (PMID 35982950, 2022). "NGS analysis of her GIST lesion revealed a quadruple wild-type tumor (no mutations in c-KIT, PDGFRA, SDH, RAS-P [RAS, BRAF, NF-1]) with a FGFR3 p.G145S mutation/variant which is of a germline rather than somatic variation." (PMID 35885469, 2022). "We performed multivariate Cox regression analysis and differential analysis of gene expression between the tumour and precancerous tissue on 11 prognostic Ras-related genes, and we got three differently expressed prognostic Ras-related genes (EGFR, RAP1B and PDGFRA)." (PMID 35281814, 2022). "Neither KIT nor PDGFRA mutations were detected by Sanger sequencing; however, next-generation sequencing (NGS) identified an FGFR2-KIAA1217 gene fusion in the tumor tissue." (PMID 35978808, 2022). "Taken together, these data indicate that the tumor immune microenvironment varies among the cancer types and is related to CNV disorders in the PDGFRA pathway, which may require attention in subsequent immunotherapy choices." (PMID 35212838, 2022). "Moreover, we detected five different gene amplifications in two different tumor specimens, including MYC (n = 2), PDGFRA, KIT, KRAS, and RICTOR." (PMID 35454843, 2022). "In this study, mutations in the genes ARID1A, APC, ERBB4, NCOR1, PDGFRA, ATM, and CDKN2A were either non-recurrent or of very low frequency, while none of the 14 sequenced EP tumours harboured mutations in the genes HRAS, EGFR, or RB1." (PMID 34045664, 2022). "When WT KIT/PDGFRA GISTS are suspected, intensive genetic analysis is recommended, and obtaining a better molecular characterization of these tumours might reveal novel therapeutic avenues." (PMID 35978808, 2022). "In turn, we found that PDGFC secreted by CAFs contributed to GIST growth, migration, and invasion via PDGFRA activation, suggesting that CAF-produced PDGFC can activate PDGFRA signaling in GIST, and this crosstalk between CAFs and GIST cells leads to a more aggressive tumor phenotype." (PMID 33603171, 2021). "Interestingly, mice with either PDGFRA or PDGFC deletion display a normalized vascular network and a significant decrease in tumor volume." (PMID 34690699, 2021). "Wild-type GIST (wtGIST) refers to tumours that are negative for KIT and PDGFRA gene mutations and account for 15% of adult and 85% of paediatric GIST." (PMID 33443647, 2021). "The CAFs expressed FSP1, but not GIST markers by IF staining and immunoblotting analysis, whereas GIST-T1 (T1) (KIT exon 11 mutant) and primary tumor cells (from a KIT-expressing PDGFRA mutant GIST) did not express FSP1." (PMID 33603171, 2021). "First, we categorized clustered data into tumor and stromal populations using a panel of markers for each (epithelial: AQP1, AQP2, EPCAM; endothelial: PLVAP, CD31, CD34; fibroblast: PDGFRα, PDGFRβ; immune: CD45; tumor cell: CXCR4, VIM, KRT18, PAX8, PAX2, CA9, CD10)." (PMID 34884982, 2021).
tumor (continued). "The tumor was diagnosed as a desmoid tumor based on positive immunohistochemical staining for β-catenin and negative staining for c-kit, CD34, platelet-derived growth factor (PDGFRα), and Discovered on GIST-1 (DOG-1)." (PMID 34526110, 2021). "Intratumoral CD8 + T-cell infiltration was significantly elevated in tumor tissues negative for PDGFRA and CXCL12 expression." (PMID 34801033, 2021). "PDGFRA and PDGFRB displayed high expression in 59% and 22% of samples, respectively, whereas high SFK phosphorylation was seen in approximately half of all tumours." (PMID 33478100, 2021). "Whereas the IDH subgroup has been singled out in many studies because of its distinct better patient survival and lower tumor proliferation rate, the lack of clustering of PDGFRA and especially of EGFRm with other RTK subgroups is surprising." (PMID 34572759, 2021). "Compared with A375 cells, A375 xenograft tumor displayed an upregulation for glial and neuronal genes (GFAP, BDNF, MAP2, MTURN, ROBO2, SYT1 and TUBB3) and neural stemness genes (ASCL1, MSI1, PAX6, PDGFRA, SOX9, VIM, ZIC1/2)." (PMID 33468253, 2021). "In addition, tumor-bearing scaffolds had a higher proportion of endothelial cells (CD45− PECAM1+) and fibroblasts (CD45− PDGFRα+) than control scaffolds." (PMID 33782087, 2021). "Using a standard protocol for monolayer tumor cell growth on tissue-culture-treated plastic in serum-containing medium, primary cell cultures were established and stained for tumor (CK18, vimentin) and fibroblast (PDGFRα/β) cell markers." (PMID 34884982, 2021). "Importantly, we demonstrate that CHSY1 selectively modulates PDGFRA signaling, and that survival of a mouse model of a CHSY1-expressing tumor is increased by using a PDGFR inhibitor." (PMID 32019907, 2020). "Coimmunoprecipitation (Co‐IP) assay confirmed that PDGFRα and IGF1R from mouse tumor OPCs could form complex (through both ectopic expression and directly testing the endogenous proteins), either through direct or indirect interaction." (PMID 33173731, 2020). "Autocrine activation of PDGFRα induced tumorigenesis and metastasis in advanced skin squamous cell carcinomas (SCCs) via upregulation and secretion of SDF-1α, and then SDF-1/CXCR4 induced PDGFR-induced tumor cell invasion and metastasis." (PMID 32754598, 2020). "Although the effect of platelet on tumor cell protrusion has not been described, the upregulation of PDGF receptor α (PDGFRα) in tumor cells undergoing EMT has been associated with invadopodia formation and stabilization." (PMID 33042789, 2020). "Then, to determine the indication of adjuvant therapy, we performed a genetic examination of the tumor, which revealed no KIT mutation but instead revealed a PDGFRA D842V substitution." (PMID 32703220, 2020). "PDGFRα and KIT, targets of the multi-kinase inhibitor sunitinib which is one of the current choices of first-line drug in metastasized ccRCC patients, were expressed at relatively low levels in tumor tissues, whereas significantly increased in normal kidney." (PMID 30881919, 2019). "Anti-PDGFRA treatment as a single agent did not reduce tumor growth and did not result in significant anti-proliferative or pro-apoptotic activity." (PMID 31331295, 2019). "Assessment of somatic copy number variants (focal homozygous deletions or ≥2-copy gain somatic copy number variants using a Log2 fold change of ≤−0.9 and ≥0.4) from the 24 WGS tumor/normal pairs revealed focal copy number gains in CFA 13 involving PDGFRA (29% WGS) and MYC (38% WGS)." (PMID 31341965, 2019). "Tumor tissue samples were examined for PDGFRA expression by IHC, but activation of PDGFRA was not assessed in the clinical study." (PMID 31331295, 2019). "Combining doxorubicin and anti-PDGFRA did not reduce tumor burden, though a mild inhibition of proliferation was observed in UZLX-STS39 and -STS59." (PMID 31331295, 2019).
tumor (continued). "Forty-nine (10%) of primary tumours had high expression of PDGFRα in both stromal and tumour cells, whereas 182 (37%) had low or absent expression of this receptor in both stromal and tumour cells." (PMID 29380207, 2018). "Yet, we found that even at the highest dose employed, Imatinib only partially inhibited PDGFRA phosphorylation and did not totally prevent mECK36 tumor growth." (PMID 29985958, 2018). "We selected 16 PDGFRA mutations which have not been studied or characterized from the TCGA, GENIE, or identified in MD Anderson Cancer Center (MDACC) patients across 15 tumor lineages." (PMID 30389923, 2018). "Mutations in putative drug targets (EGFR, PDGFRA, ERBB2, and PI3K) are not always stable between primary and recurrence tumors, supporting tumor evolution during progression." (PMID 30279357, 2018). "Surprisingly, analysis of mECK36 tumor tyrosine kinase activation showed a prominently activated RTK spot that accounted for a significant portion of the total tyrosine kinase activation of the tumor, which corresponded to the PDGF receptor alpha-chain (PDGFRA)." (PMID 29985958, 2018). "Tumour cells showed high expression of PDGFRα in 76 (56%) and PDGF-CC in 29 (22%) of synchronous lymph node metastasis, whereas stromal cells showed high expression of PDGFRα in 68 (50%) and PDGFRβ in 46 (34%)." (PMID 29380207, 2018). "Additionally, targets such as PDGFRA, which are typically overexpressed in clinical cases of RMS, appear crucial to tumor progression when tested in vitro." (PMID 28883017, 2017). "PDGFRα and EMT markers were detected in the tumor tissues derived from mice." (PMID 28415580, 2017). "Third, following PDGFRα downregulation by DHA, the downstream PI3K/AKT and MAPK/ERK signaling pathways were inactivated and the EMT was repressed, resulting in suppression of the tumor growth and migration." (PMID 29387451, 2017). "Our results suggest that PDGFRα overexpression in HCC is a prognostic marker independent of adjacent non-tumor site liver fibrosis status." (PMID 28465473, 2017). "A recent study revealed that PDGF-AA expression and phosphorylation of PDGFRα without any gene alteration led to AKT activation through an autocrine/paracrine-mediated loop in a subset of clinical SS tumour samples." (PMID 28511645, 2017). "There was a significant difference in PDGFRα expression of tumor and non-tumor sites and strong expression of PDGFRα was not seen in non- tumor sites." (PMID 28465473, 2017). "We also identified three tumors with targetable RTK lesions (PDGFRA, ERBB2, ERBB4) that were exclusive to the recurrent tumor (HGG5, HG8, HGG11), indicating that genomic data from tumor tissue at recurrence may provide better guidance for therapeutic choices." (PMID 29084603, 2017). "It has been reported that multiple membrane receptors, including PDGFRα, could provoke EMT progression and enhance tumor metastasis." (PMID 29387451, 2017). "Increase of PDGFRα expression has been reported in cancerous hepatocytes, while another study demonstrated that they were non-parenchymal cells in tumor sites where PDGFRα were expressed." (PMID 28465473, 2017). "Besides a role of PDGFRα in glial differentiation, the block of PDGFRα activity in vitro promoted the reduction of NG2 expression and tumor cells growth as reported by Pilkington." (PMID 27344175, 2016). "Although the PDGFRA role in GIST and IFP pathogenesis justifies the presence of these two tumor types in PDGFRA-mutant syndrome, the occurrence of GI lipomas (sporadic GI lipomas revealed PDGFRA WT) and large hands, and the variability of the observed phenotypic assortment are presently unexplained." (PMID 27437068, 2016). "The tumour from patient #2 presented variable 5–10 fold amplification across 4q12, which included the tyrosine kinase KIT, and tyrosine kinase receptors PDGFRA and KDR (VEGFR2)." (PMID 27843499, 2016).